ABCB1 (ATP binding cassette subfamily B member 1)
Diseases named in the same sentence as ABCB1 in open-access papers (continued):
Sharing a sentence is not in itself a finding about the gene and the disease.
cancer (continued). "PD173074 is a potent inhibitor of FGFR1 and VEGFR, and it was also shown to effectively resensitize chemoresistant cancer cells overexpressing ABCB1 and ABCC10 to some chemotherapeutic agents, including paclitaxel." (PMID 41154409, 2025). "Cancer cells resistant to other anthracyclines based on the ABCB1 overexpression mechanism is believed to maintain sensitivity against ACLA." (PMID 40629205, 2025). "Of particular significance is the fact that overexpression of ABCB1 constitutes a crucial factor in developing MDR in cancer cells." (PMID 40427071, 2025). "Chromosomal amplification and ABCB1 expression can arise as adaptive responses to drug exposure, promoting the survival and proliferation of resistant cancer cells under chemotherapy." (PMID 41114937, 2025). "Upregulated levels of the glucosylceramide synthase (GCS), an enzyme that functions in sphingolipid metabolism, lead to the upregulated ABCB1 gene that induces drug efflux from the cancer cells." (PMID 40332322, 2025). "P-gp or the ATP-binding cassette (ABC) transporter (ABCB1) prevents cellular uptake of a variety of anticancer drugs, leading to cancer drug resistance." (PMID 40006556, 2025). "Elevated expression levels of ABCB1 in cancer cells drive chemoresistance by facilitating the active efflux of chemotherapeutic drugs, thereby depleting their intracellular concentrations." (PMID 40427071, 2025). "Previous studies have shown that BLU-258 at non-toxic concentrations can impair the function of the ATP-binding transporters (ABC) ABCB1 and ABCG2 in vitro and restore chemosensitivity in multidrug-resistant cancer cells overexpressing ABCB1 and ABCG2." (PMID 40076604, 2025). "In the present study, we aimed to elucidate the mechanisms by which melatonin overcomes ABCB1‐mediated MDR in cancer cells, with a focus on mitochondrial function." (PMID 41189280, 2025). "In recent decades, three generations of ABCB1/P-gp inhibitors have been developed, some of which are currently undergoing clinical trials to evaluate their role in circumventing anti-cancer resistance." (PMID 38611964, 2024). "Treatment of the cells with cordycepin was able to modulate P-gp expression and inhibit its function by stimulating P-gp ATPase activity in cells stably expressing P-gp (ABCB1/Flp-InTM-293) and in cancer cells with a multidrug resistance profile (KB-vin)." (PMID 38534354, 2024). "Overall, the findings demonstrated that FRAX486 overcame MDR in cancer via regulating ABCB1 function and enhancing drug accumulation in resistant cells." (PMID 38958364, 2024). "The development of safer and more potent compounds to ABCB1 will be critical for successful clinical application of PROTAC degraders for cancer therapy." (PMID 38557192, 2024). "Thirdly, we need to ensure that C3N-Dbn-Trp2 and its derivatives can efficiently promote the killing of cancer cells with chemotherapeutic drugs while minimizing side effects on normal cells expressing ABCB1 in the body." (PMID 39003409, 2024). "SRI is located on the same gene locus as ABCB1 and is often co-amplified in multidrug-resistant cancers." (PMID 38163893, 2024). "Second, studies are ongoing to identify cancer-specific regulators of ABCB1 expression for their potential targeted deactivation." (PMID 39090086, 2024). "ABCB1 is primarily known for its role in conferring multidrug resistance in cancer by specifically expelling chemotherapeutic agents out of cells, thereby abating intracellular drug accumulation and diminishing therapeutic efficacy (Chen H-K." (PMID 39679367, 2024). "We present data on cancer chemotherapy-related pharmacogene variant frequencies in DPYD, UGT1A1, TPMT, NUDT15, and ABCB1 within the Chilean population, offering insights for the strategic implementation of pharmacogenetic testing." (PMID 38675222, 2024). "The ABCB1 gene, encoding the P-glycoprotein transporter (MDR1/ABCB1), plays a pivotal role in drug transport and has implications for drug response and cancer risk." (PMID 38675222, 2024).
cancer (continued). "ABCB1 can transport a variety of substrates out of cells via ATP-hydrolysis including a broad range of molecules, including multiple anti-cancer drugs, such as vincristine, actinomycin-D, paclitaxel, CBZ and DTX." (PMID 39090086, 2024). "Both ABCB1 and CYP1B1 exhibit associations with microRNAs in cancer and the Nuclear Receptors Meta-Pathway (WP2882)." (PMID 38534761, 2024). "Our results showed shikonin induces apoptosis in these ABCB1-dependent and independent chemoresistance cancer sublines." (PMID 38203787, 2024). "ABC transporters, particularly ABCB1 and ABCC1, are widely expressed in multiple cancer types and are strongly implicated in multidrug resistance, which severely limits the effectiveness of chemotherapy." (PMID 39679367, 2024). "Our unique approach presents a promising lead toward developing effective ABCB1 inhibitors to treat drug-resistant cancers." (PMID 39003409, 2024). "This inhibition can potentially disrupt the normal functioning of ABCB1, leading to enhanced drug accumulation and overcoming drug resistance in cancer cells." (PMID 38958364, 2024). "Further studies revealed that high ATP-binding cassette subfamily B member 1 (ABCB1) expression in cancer cells was positively correlated with drug resistance in ALL." (PMID 38286894, 2024). "Similar to cancer cells that elevate ABCB1 expression during chemotherapy, T-cells also elevate ABCB1 expression during prolonged treatment with HIV-1 inhibitors and gain drug resistance." (PMID 39003409, 2024). "In our research, we discovered that stachybotrysin B had a reversal effect on MDR in ABCB1-overexpressing cancer cells." (PMID 38611964, 2024). "Amplification of this region is observed in many multidrug-resistant cancers, leading to the overexpression of both sorcin and ABCB1, further contributing to MDR." (PMID 39199583, 2024). "This compound achieved similar specificity and efficacy to the widely known ABCB1 inhibitor, verapamil in restoring sensitivity to chemotherapeutic drugs in drug-resistant cancer cells expressing ABCB1." (PMID 39003409, 2024). "Several tryptophan derivatives designed by structure-guided computational modelling of human ABCB1-ligand binding efficiently inhibited ABCB1 in human cancer cells and sensitised them to chemotherapeutic agents." (PMID 39003409, 2024). "Since the discovery of its multidrug efflux function, ABCB1 has remained a key focus in cancer therapy." (PMID 38397468, 2024). "Chemotherapy is a powerful means of cancer treatment but its efficacy is compromised by the emergence of multidrug resistance (MDR), mainly linked to the efflux transporter ABCB1/P-glycoprotein (P-gp)." (PMID 38167542, 2024). "Therein, this study reported for the first time, that circulating transcripts of ABCB1 are traceable in liquid biopsies, advancing a new dimension for systemic monitoring of ABCB1 expression in cancer patients." (PMID 39580452, 2024). "The mechanism of action of furmonertinib was characterized through ATPase assays, revealing its interaction with ABCB1 and ABCG2,suggesting a potential strategy to overcome resistance in EGFR exon 20ins-mutated cancers." (PMID 39743996, 2024). "Due to the synergistic effect, the expression of ATP‐binding cassette subfamily B member 1 (ABCB1) is reduced and the drug resistance pathway is broken, resulting to the efficient cancer treatment." (PMID 38898730, 2024). "P-glycoprotein (P-gp)/ABCB1 is an ABC transporter protein that acts as a vital determinant of the multidrug resistance phenotype of cancer cells." (PMID 38521878, 2024). "This study intended to elucidate the potential of FRAX486 as a reversal agent for multidrug resistance mediated by ABCB1, as well as its therapeutic potential in overcoming drug resistance and improving cancer patient treatment outcomes." (PMID 38958364, 2024).
cancer (continued). "Previously, multiple studies have shown that some critical signaling pathways in cells can be involved in the development of multidrug resistance in cancer cells through the regulation of ABCB1." (PMID 38228910, 2024). "Our idea stems from our studies on bat cells, as bats have low cancer incidences and high ABCB1 expression." (PMID 39003409, 2024). "P-glycoprotein (P-gp), also known as multidrug resistance protein (MDR1), is a type of adenosine triphosphate (ATP)-coupling cassette transporter (ABCB1) that is extensively studied due to its role in limiting effective cancer pharmacotherapy." (PMID 39339174, 2024). "Studies have demonstrated that CRISPR-Cas9-mediated knockout of ABCB1 in various cancer cell lines increases sensitivity to several drugs." (PMID 39726634, 2024). "Normally polarized apical-in cancer clusters display apically located multidrug resistance transporters, such as the efflux transporter ATP binding cassette subfamily B member 1 (ABCB1), on the lumen-facing membranes." (PMID 38465512, 2024). "The successful development of effective therapeutic strategies against multidrug-resistant cancers, such as those mediated by overexpression of ABCB1, remains a critical challenge in the field of cancer treatment." (PMID 39206391, 2024). "ABCB1 is highly expressed in various types of cancer and serves as one of the indicators of chemotherapy resistance." (PMID 39507258, 2024). "This study delves into the expression of drug resistance-associated genes, ABCB1 and CYP1B1, in cancer cells." (PMID 38534761, 2024). "Research has illuminated its role in modulating paclitaxel resistance in TNBC via the miR-206/ABCB1 axis, with ABCB1 being a quintessential chemotherapy resistance protein found in multidrug-resistant cancers." (PMID 39286016, 2024). "Conversely, the downregulation of ABCB1 in cancer cells leads to increased chemosensitivity to 5-FU, epirubicin, irinotecan and oxaliplatin, drugs that are still commonly used in the treatment of gastrointestinal carcinomas." (PMID 36983038, 2023). "In another study, a polyglutamine-based co-polymer gene delivery system was developed for cancer therapy to deliver interfering siRNA agents against multidrug resistance protein 1 (MDR1/P-gp/ABCB1) and survivin." (PMID 36770817, 2023). "All of these studies together indicate that the Wnt/β-catenin pathway regulates ABCB1 expression across multiple cancer types and chemotherapies." (PMID 37686513, 2023). "In this in vitro study, we conducted in vitro experiments to determine if MK-2206 attenuates multidrug resistance in cancer cells overexpressing the ABCB1 or ABCG2 transporter." (PMID 37521473, 2023). "This research shows that ABCB1 overexpression can be due to chromosome 7 amplifications across multiple different cancer types that are resistant to different chemotherapeutic agents." (PMID 37686513, 2023). "In this review, we summarize current knowledge of genetic and epigenetic mechanisms leading to ABCB1 upregulation and P-gp-enhanced ATPase activity in the setting of chemotherapy resistance across a variety of cancers." (PMID 37686513, 2023). "Drug efflux pumps, such as ABC transporters, ABCG2 or ABCB1, are activated in SP cells and help to efflux various cancer drugs, thereby generating a multidrug resistance phenotype." (PMID 36605488, 2023). "ABCB1/MDR1/P-glycoprotein (Pgp) is a drug efflux transporter responsible for multidrug resistance in cancer chemotherapy and drug efflux at the BBB." (PMID 37242805, 2023). "Overexpression of ABCB1 has been correlated with chemoresistance in several different cancers, including breast, kidney, colon, adrenal, pancreas, liver, prostate, and ovarian." (PMID 36831661, 2023). "It has the capability to sensitize multidrug-resistant cancer cells that overexpress ABCB1 and ABCG2 to cytotoxic anticancer drugs by attenuating their drug efflux function." (PMID 37762275, 2023).
cancer (continued). "Results demonstrate that ABCB1 was down-regulated after treatment with ICG for 30 min in cancer cell lines." (PMID 37228164, 2023). "When expressed in cancer cells, ABCB1 can prevent the intracellular accumulation of drugs, including frontline chemotherapeutic agents such as doxorubicin, paclitaxel, and vincristine." (PMID 36982374, 2023). "The role of AKT1, a downstream element of the phosphoinositide-3-kinase (PI3K) cascade, in the upregulation of ABCB1 is strongly established in cancer models in link with chemotherapeutic resistance mechanism." (PMID 37408070, 2023). "Researchers propose repurposing existing drugs to sensitize multidrug-resistant cancer cells, which overexpress ABCB1 or ABCG2, to conventional anticancer drugs." (PMID 37762275, 2023). "P-glycoprotein (Pgp, also referred to as MDR1 and ABCB1) and Multidrug resistance protein 1 (MRP1) are critical multidrug resistance in mammalian cancer cells, and these transporters can efflux several different types of medicines." (PMID 37367772, 2023). "Factors leading to Pt resistance are various, including angiogenesis, hypoxia, immune infiltration, and abnormal regulation of breast cancer susceptibility gene (BRCA), ATP binding cassette subfamily B member 1 (ABCB1) and cyclin E1 (CCNE1), etc.." (PMID 36959862, 2023). "The activation of this intracellular pathway increases the production of the ATP-biding cassette, subfamily B, member 1 (ABCB1), a multidrug efflux transporter that attenuates the effect of cytotoxic drugs in cancer cells." (PMID 37892239, 2023). "The authors do not provide a possible causal mechanism explaining the effect of a decrease in the level of ABCB1 gene expression on the proliferation, migration, survival, or invasion of cancer cells." (PMID 36674773, 2023). "As an example, ABCB1, or MDR1 (also known as P-glycoprotein), has been extensively studied in part due to its broad substrate specificities and linkages to therapeutic resistance in cancers, including limited reports in EAC." (PMID 38139823, 2023). "Recently, drug repurposing has emerged as a feasible strategy to overcome ABCB1- or ABCG2-mediated drug resistance in cancer." (PMID 37521473, 2023). "IMA is also a substrate of P-glycoprotein (Pgp - ABCB1) which mediates its re-extrusion into the intestinal lumen and elimination from cancer cells." (PMID 37318715, 2023). "As the first step in this study, we determined the cytotoxicity of HS-173 in multiple paired parental cancer cell lines and respective sublines expressing either ABCB1 or ABCG2." (PMID 37048130, 2023). "We also observed that the expression of ABCB1 was down-regulated in cancer cells after a 30-minute ICG treatment." (PMID 37228164, 2023). "In vitro work across a wide range of drug-sensitive and -resistant cancer cell lines has shown that upon treatment with chemotherapeutic agents such as doxorubicin, cisplatin, and paclitaxel, ABCB1 is upregulated." (PMID 37686513, 2023). "A multitude of natural products have demonstrated the ability to reverse MDR in cancer cells that overexpress ABCB1 and ABCG2." (PMID 38004460, 2023). "In particular, demethylation of the ABCB1 gene in cancer cells can lead to a reduction in the accumulation of anticancer drugs in cancer cells, resulting in the acquisition of a resistant phenotype." (PMID 38264526, 2023). "Other plant-based polyphenols have been reported to modulate the gene expression of ABCB1, altering P-gp levels and impacting drug bioavailability and the response of cancer cells to chemotherapeutic treatment." (PMID 38139823, 2023). "ABCB1 (also known as P-glycoprotein/P-gP) and ABCC1 (MRP-1) were the first ABC transporters directly linked to a MDR phenotype in cancer cells." (PMID 37047018, 2023). "P-gp/ABCB1 overexpression increases energy-based cytotoxic drug efflux from cancer cells, thereby enhancing drug resistance." (PMID 37067729, 2023).
cancer (continued). "Many cytotoxic chemotherapeutic drugs can be pumped out of cancer cells by ABCB1 and ABCCs, such as taxanes, vinca alkaloids, and anthracyclines." (PMID 37229486, 2023). "This review discusses the use of low-dose bipolar drugs in sensitizing ABCB1-overexpressing, drug-resistant cancers." (PMID 37176096, 2023). "First, we found from the data that the ABCB1-overexpressing KB-V1 human epidermal cancer cells were significantly resistant to HS-173 treatment (RF = 11) as compared to the parental KB-3-1 cancer cells." (PMID 37048130, 2023). "Cross-resistance in cancer is often due to the expression of the multi-drug resistance protein MDR1, encoded by the gene ABCB1." (PMID 38139368, 2023). "ATP binding cassette subfamily B member 1 (ABCB1) expression is indicated to be closely related to the drug resistance of cancer cells." (PMID 38007504, 2023). "We found that the overexpression of ABCB1 or ABCG2 significantly reduced the efficacy of HS-173 in human cancer cells." (PMID 37048130, 2023). "This short review mainly focuses on those three ABC transporter members (ABCB1, ABCC1 and ABCG2), which are predominantly linked to the phenomenon of MDR in cancer therapy." (PMID 36677553, 2023). "Acerinol isolated from C. acerina can potentially reverse the ABCB1-mediated multidrug resistance (MDR) in cancer cells." (PMID 38139334, 2023). "We also focus on the genetics of ABCB1, reviewing publicly available data to understand the prevalence of ABCB1 alterations across different cancers, alongside common mechanisms by which ABCB1 has been found to be upregulated in multidrug-resistant cancers." (PMID 37686513, 2023). "The present data lay the groundwork for future development of new classes of modulators of the ABCB1 efflux pump with potential clinical relevance, as they can improve the efficacy of chemotherapy in resistant cancers." (PMID 36674503, 2023). "Dysregulated noncoding RNAs, including microRNAs (miRNAs) and long noncoding RNAs (lncRNAs), have been found to be associated with the overexpression of ABCB1, ABCG2, and ABCCs in chemoresistant cancers." (PMID 37229486, 2023). "Although considered as a first-line drug for various types of cancers, one of the main obstacles to doxorubicin therapy is drug resistance, which is mainly mediated by ABCB1, for which doxorubicin represents a good substrate." (PMID 36674503, 2023). "Treatment with tariquidar or Ko143 was able to restore the activity of HS-173 to induce cell apoptosis in KB-V1 and S1-MI-80 cancer cells by inhibiting the drug transport function of ABCB1 and ABCG2, respectively." (PMID 37048130, 2023). "For further biological investigations, we have used cancer cell lines with different amounts of ABCB1 and ABCG2 expression levels." (PMID 38004447, 2023). "To this end, we examined the effect of HS-173 on MDR mediated by ABCB1 and ABCG2 in cancer cells overexpressing ABCB1 or ABCG2." (PMID 37048130, 2023). "To explore the prevalence of ABCB1 dysregulation in cancer, we utilized the NCI’s publicly available GDC Data Portal." (PMID 37686513, 2023). "P-glycoprotein, product of the ABCB1 (ATP binding cassette subfamily B member 1) gene, has been reported to play an important role in multiple drug resistance during cancer therapy." (PMID 36755808, 2023). "In the present work, we identified two out of three tested cancer associated ABC transporters, ABCB1/MDR1 and ABCG2/BCRP, as off-targets of the OGG1 inhibitors TH5487 and SU0268." (PMID 36819096, 2023). "Cancer cells can do this by increasing the expression of ABCB1 genes, also referred to as multidrug resistance (MDR1) genes." (PMID 37190285, 2023). "P-glycoprotein (P-gp, MDR1, ABCB1) first caught the attention of scientists because of its involvement in the multidrug resistance (MDR) phenotype of cancer cells." (PMID 37569709, 2023).